ADA2 (adenosine deaminase 2)
Diseases named in the same sentence as ADA2 in open-access papers (continued):
Sharing a sentence is not in itself a finding about the gene and the disease.
COVID-19 (7 papers, 2021 to 2026). A disease caused by infection with severe acute respiratory syndrome coronavirus 2. "Consistent with our findings, these works suggest an important role of ADA2 signaling in modulating the hypoxic and severe condition of COVID-19-associated ARDS." (PMID 40332245, 2025). "In our study, rs5994195 in the intron of ADA2 was identified to be associated with IgG level of COVID-19 vaccine immunization." (PMID 36451823, 2022). "We describe the case of an 11-year-old girl with adenosine deaminase 2 deficiency who presented severe COVID-19 acute respiratory distress syndrome, complicated by a massive air leak syndrome." (PMID 34778132, 2021). "To further elucidate the role of ADA2, we analyzed the previously published spatial atlas and single-cell RNA sequencing (scRNAseq) data from COVID-19 lung tissue." (PMID 40332245, 2025). "Previous scRNAseq data showed that ADA2 expression was upregulated in inflammatory CD14high/CD16high monocytes in COVID-19 lungs." (PMID 40332245, 2025). "Further analyses revealed that among the myeloid cell population, inflammatory CD14high/CD16high monocytes exhibited the highest expression of ADA2 in COVID-19 lungs." (PMID 40332245, 2025). "A spatial atlas of COVID-19 lungs showed that ADA2 expression was increased in areas of inflamed alveoli as compared to normal-appearing alveoli." (PMID 40332245, 2025). "Studies have detected elevated levels of tADA and its isoenzymes ADA1 and ADA2 in saliva in patients diagnosed and convalescent with the new coronavirus disease 2019 (COVID-19)." (PMID 36260871, 2022). "ADA2 may serve as a biomarker for disease progression and a therapeutic target to modulate macrophage-driven inflammation in severe COVID-19." (PMID 42083558, 2026). "We further determined ADA2+ cells in COVID-19 lungs using a published scRNAseq dataset." (PMID 40332245, 2025). "The correlation between ADA isoenzyme pattern in the serum of post-COVID patients and the proportion of circulating monocytes should be further examined in order to assess whether ADA2 could be used as an indicator of deregulated proinflammatory cytokine production in post-COVID-19 individuals." (PMID 37685949, 2023). "By using published datasets of spatial transcriptomics and single-cell RNAseq, we show that ADA2 is highly expressed by inflammatory CD14+CD16+ monocytes, along with profibrotic genes, in lungs affected by COVID-19." (PMID 40332245, 2025). "However, this is not so strange since it has recently been reported that tADA and ADA2 levels change in serum of individuals 8 weeks after diagnosis of acute COVID-19 by PCR, whereas ADA1 levels do not change." (PMID 38881733, 2024).
tuberculous pleurisy (7 papers, 2010 to 2025). "This test can also be used to diagnose pleural tuberculosis or other diseases with significantly elevated ADA2 levels." (PMID 40936927, 2025). "As shown in our study, pleural ADA2 yielded the great sensitivity of 76.6% and the highest specificity of 97% on the diagnosis of tuberculous pleurisy." (PMID 24984978, 2014). "Most of the ADA in pleural tuberculosis is ADA2; although better than total ADA for diagnosing pleural tuberculosis, the separation of ADA into its isoenzymes is more expensive than the basic ADA test, not readily available and its use is so far limited." (PMID 22723878, 2012). "ADA-2 isoform is the one raised in tuberculous pleurisy, accounting for almost 88% of total ADA activity." (PMID 21811524, 2010). "For example, increased ADA2 activity has been used to diagnose pleural tuberculosis." (PMID 40936927, 2025). "Currently, ADA2 activity can be used to diagnose pleural tuberculosis." (PMID 40936927, 2025). "Therefore, ADA2 increases primarily in tuberculous pleurisy, while ADA1 increases primarily in lymphoma." (PMID 41480553, 2025). "The accumulation of ADA in pleural fluid results mainly from one of its isoforms, ADA2, with which a diagnosis of tuberculous pleurisy could be verified." (PMID 24984978, 2014). "Additionally, we demonstrate that this test could potentially be used to diagnose other diseases, such as pleural tuberculosis, where ADA2 levels are significantly elevated." (PMID 40936927, 2025). "The development of an ADA2 rapid antigen test represents a significant advancement in point-of-care diagnostics, particularly for the diagnosis of DADA2 and the screening of pleural tuberculosis." (PMID 40936927, 2025).
viral infections (7 papers, 2020 to 2024). "Altered ADA2 enzyme activity has been associated with some viral infections and rheumatic diseases." (PMID 32650798, 2020). "Elevated serum isoenzyme ADA2 is commonly found in viral diseases, such as immunodeficiency virus infections." (PMID 36260871, 2022). "Serum increases of ADA2 activity has been described in patients with bacterial and viral diseases, including individuals with SARS-CoV-2 infection and who recovered from infection." (PMID 36451823, 2022). "Relatedly, previous studies have shown that Spt–Ada–Gcn5 acetyltransferase (SAGA), a universal transcriptional coactivator, upregulates CpDcl2 upon hypovirus infection, and knockout of SAGA subunits Gcn5, Sgf73, and Ada2 abolished any induction of CpDcl2 transcription upon viral infection." (PMID 38784801, 2024). "The reported EBV-related lymphomas may indicate an indirect role for ADA2 in defense against viral infections." (PMID 37277582, 2023).
hemophagocytic lymphohistiocytosis (6 papers, 2021 to 2026). "The defect in ADA2-deficient cytotoxic lymphocytes may also explain why some DADA2 patients present with hemophagocytic lymphohistiocytosis (unpublished observation) or CD3+CD8+ large granular lymphocytes." (PMID 34657246, 2021). "The defect in ADA2-deficient cytotoxic lymphocytes may be also linked to rare DADA2-associated manifestations, such as hemophagocytic lymphohistiocytosis (HLH) or CD3+ CD8+ large granular lymphocytes." (PMID 35898506, 2022).
systemic vasculitis (6 papers, 2014 to 2025). "Deficiency of adenosine deaminase 2 (DADA2) is a recessively inherited autoinflammatory disease caused by a functional loss or mutation of the ADA2 gene, resulting in systemic vasculitis." (PMID 41008570, 2025). "In a systemic vasculitis known as deficiency of ADA2, NETs induced production of inflammatory cytokines from macrophages through NF-κB nuclear translocation in macrophages." (PMID 35941120, 2022). "An ADA2 deficiency could have explained the vascular aneurysms and necrotizing vasculitis on histology, but its isolated pulmonary arterial presentation without skin lesions or neurological manifestations seems unlikely." (PMID 40810771, 2025). "Deficiency of adenosine deaminase 2 (DADA2) is caused by ADA2 gene mutations, resulting in an autoinflammatory systemic vasculitis, where neutrophil extracellular traps (NETs) significantly contribute to the disease." (PMID 37759787, 2023).
glioblastoma (5 papers, 2019 to 2022). The most malignant astrocytic tumor (WHO grade IV). "Moreover, ADA2/CECR1 mediates cross-talk between macrophages and pericytes in glioblastoma multiforme resulting in pericyte recruitment and migration, and thus promoting tumor angiogenesis." (PMID 34054547, 2021). "ADA2 was significantly increased in esophageal carcinoma (ESCA), glioblastoma multiforme (GBM), LAML, OV, PAAD, skin cutaneous melanoma (SKCM), and STAD." (PMID 35663977, 2022). "ADA2 expression was significantly increased in esophageal carcinoma (ESCA), glioblastoma multiforme (GBM), acute myeloid leukemia (LAML), OV, PAAD, skin cutaneous melanoma (SKCM), and stomach adenocarcinoma (STAD)." (PMID 35663977, 2022).
hypogammaglobulinemia (5 papers, 2021 to 2025). "Collectively, these data demonstrating an intrinsic maturation B cell defect due to ADA2-deficiency may explain the hypogammaglobulinemia and B cell lymphopenia characteristic of DADA2 patients." (PMID 34657246, 2021).
macrophage activation syndrome (5 papers, 2022 to 2025). A complication of rheumatic disease that is caused by excessive activation and uncontrolled proliferation of T lymphocytes and well-differentiated macrophages. "High levels of ADA2 have been reported in association with infectious and inflammatory illnesses including macrophage activation syndrome in systemic-onset juvenile idiopathic arthritis." (PMID 38390319, 2024). "One study suggests that ADA2 activity can be used as a biomarker for macrophage activation syndrome in patients with systemic JIA." (PMID 35090387, 2022). "Further, plasma ADA2 activity can be used as a biomarker for macrophage activation syndrome in systemic JIA patients." (PMID 35090387, 2022).
primary immunodeficiencies (5 papers, 2021 to 2025). "Deficiency of Adenosine Deaminase 2 (DADA2) patients presenting with primary immunodeficiency are at risk of uncontrolled EBV infection and secondary malignancies including EBV-related lymphoproliferative disorders (LPD)." (PMID 38758417, 2024). "Genetic evaluation for primary immunodeficiencies showed biallelic pathogenic ADA2 variants." (PMID 37277582, 2023). "Primary immunodeficiency disease panel or whole-exome sequencing was performed for suspected cases, and assays for adenosine deaminase 2 (ADA2) enzyme activity were also carried out for the patients and their parents." (PMID 33757531, 2021). "With further validation in screening for DADA2 in patients with primary immunodeficiencies, the ADA2 RAT could pave the way for accessible, home-based healthcare solutions, improving disease outcomes through timely diagnosis and intervention." (PMID 40936927, 2025).
red cell aplasia (5 papers, 2020 to 2023). "Our results provide further proof of concept for the efficacy of gene transfer strategies for the treatment of DADA2 using LV and the EFS promoter, which rescued stem cells and their progeny from a patient with ADA2-associated red cell aplasia." (PMID 35529868, 2022). "Patients with ADA2 variants present with a lack of erythroid precursors with maturation arrest in infancy, consistent with pure red cell aplasia, but they do not exhibit dysmorphic traits and, most importantly, they feature normal rRNA maturation." (PMID 38002903, 2023).
diabetes (4 papers, 2014 to 2020). "The deaminase activity of ADA1 and ADA2 was determined in serum from 33 patients with type 2 (or II) diabetes mellitus and 35 healthy controls." (PMID 28050278, 2016). "We identified a role of miR-146b-3p in the regulation of retinal inflammation in diabetes by suppressing ADA2." (PMID 25815338, 2015). "Total serum ADA activity, specially that due to ADA2, could be useful test for the diagnosis of type 2 (or II) diabetes mellitus." (PMID 28050278, 2016). "ADA increase, especially ADA2, may serve as an immunoenzyme marker in the pathology of type 2 diabetes mellitus." (PMID 28050278, 2016). "ADA2 is strongly increased in inflammatory diseases such as rheumatoid arthritis and tuberculosis, AIDS, and diabetes." (PMID 28050278, 2016). "ADA2 activity is elevated significantly in pleural fluids of patients with pulmonary tuberculosis, sera from HIV-infected individuals, and from patients with diabetes, making ADA2 activity a convenient marker to improve the diagnosis and follow-up treatment of these disorders." (PMID 25815338, 2015). "However, because ADA2 gene has not been identified in mouse genome, how diabetes alters adenosine-dependent anti-inflammation remains unclear." (PMID 25815338, 2015).
hemorrhagic stroke (4 papers, 2021 to 2024). A stroke caused by a bleed on the brain. "Deficiency of ADA2 arises from mutations affecting catalytic activity, protein dimerization, and secretion of ADA2 and causes vasculopathy and inflammation in many organs and/or hemorrhagic stroke." (PMID 34054547, 2021).
respiratory infections (4 papers, 2018 to 2024). "A 6-protein diagnostic panel, comprising FETUB, FCGR3B, LRG1, SELL, CD14, and ADA2, differentiated patients with pulmonary TB from healthy controls and patients with other respiratory infections with high sensitivity and specificity in both cohorts." (PMID 38512356, 2024). "Schepp and colleagues subsequently found compound heterozygous ADA2 mutations with absent plasma ADA2 activity in an adult with hypogammaglobinemia and recurrent respiratory infection." (PMID 30406060, 2018). "However, analysis of saliva of children with tonsillitis and respiratory infections did not reveal any difference in ADA2 concentration." (PMID 35967411, 2022). "In addition, children with tonsillitis and respiratory infections had a similar concentration of ADA2 to healthy controls, suggesting that these infections do not affect the concentration of ADA2 in saliva." (PMID 35967411, 2022).
systemic lupus erythematosus (4 papers, 2022 to 2025). An autoimmune multi-organ disease typically associated with vasculopathy and autoantibody production. "If the risk probability exceeds 0.766, it should raise a strong suspicion of monogenic lupus, prompting the timely completion of genetic testing and additional diagnostic evaluations including the mRNA expression of IFN-stimulated genes and ADA2 levels, among others." (PMID 38970732, 2024).
autoimmune disease (3 papers, 2018 to 2020). A disorder resulting from loss of function or tissue destruction of an organ or multiple organs, arising from humoral or cellular immune responses of the individual to their own tissue constituents. "Similar to AGS, another genetic autoimmune disease has been characterised in zebrafish: deficiency of Adenosine Deaminase 2 (ADA2)." (PMID 32632777, 2020). "Elevated plasma ADA2 concentrations are associated with infection, autoimmune diseases, and malignancy, but whether ADA2 plays a role in these inflammatory processes is not clear." (PMID 30406060, 2018).
Autoimmunity (3 papers, 2017 to 2024). The occurrence of an immune reaction against the organism's own cells or tissues. "Our patient exhibited no hypogammaglobulinemia, no biological markers of autoimmunity (ANA/lupus anticoagulant), and no recurrent infections, even though there was B‐cell lymphopenia in accordance with the proposed hypothesis that ADA2 deficiency may lead to a defect in memory B cells." (PMID 35261770, 2022).
breast carcinoma (3 papers, 2021 to 2025). "Clinical studies have also shown that the levels of ADA2 in biological fluids are increased in other pathophysiological conditions, such as HIV infection and breast cancer and dramatically decreased in patients with ADA2 deficiency (DADA2)." (PMID 40895545, 2025). "Several lines of evidence suggest that altered adenosine deaminase (ADA) activity, especially its ADA2 iso-enzyme, is associated with malignant breast cancer (BC) development." (PMID 33916440, 2021). "The patients with TNBC revealed higher plasma ADA2 activities at advanced stages of cancer development than in the initial stages and exhibited low ADA1/ADA2 ratio, while patients with HR+HER2+ and HR+HER2- breast cancers at the same stages showed opposite trends." (PMID 33916440, 2021).
chronic granulomatous disease (3 papers, 2023). Chronic granulomatous disease (CGD) is a rare primary immunodeficiency, mainly affecting phagocytes, which is characterized by an increased susceptibility to severe and recurrent bacterial and fungal infections, along with the development of granulomas. "It has also been described in genetically diverse IEIs including ataxia telangiectasia, NFKB1 haploinsufficiency, ADA2 deficiency, CD40 ligand deficiency, activated PI3K delta syndrome, STAT3 gain of function and chronic granulomatous disease (CGD)." (PMID 38068532, 2023). "For example, the PM2 score was highly elevated in deficiency of adenosine deaminase 2 (DADA2) patients and several PIDs such as STAT1 gain-of-function (STAT1 GOF) and X-linked chronic granulomatous disease (X-CGD), relative to healthy subjects." (PMID 36993430, 2023).
diabetic retinopathy (3 papers, 2014 to 2021). "Retinal inflammation in diabetic retinopathy is mediated by ADA2 and the anti-inflammatory activity of A2AR signalling is impaired with increased ADA2 activity." (PMID 28993732, 2017).
lymphoma (3 papers, 2023 to 2025). A malignant (clonal) proliferation of B- lymphocytes or T- lymphocytes which involves the lymph nodes, bone marrow and/or extranodal sites. "While most malignancies show low ADA2 levels, this exception emphasizes the need for careful interpretation, especially when lymphoma is suspected." (PMID 40895545, 2025). "Interestingly, among malignant pleural effusions, lymphoma exhibited significantly higher ADA2 concentrations." (PMID 40895545, 2025).
lymphopenia (3 papers, 2016 to 2022). Reduction in the number of lymphocytes. "According to previous research, ADA2 deficiency is frequently linked to lymphopenia (including CD8 memory cells, T cells, and follicular T cells)." (PMID 36243706, 2022).
Pancytopenia (3 papers, 2021 to 2025). An abnormal reduction in numbers of all blood cell types (red blood cells, white blood cells, and platelets). "After genetic testing showed biallelic pathogenic variants in the ADA2 gene, the patient developed pancytopenia and a perianal fistula probably due to inflammatory bowel disease (IBD) in the context of DADA2." (PMID 37277582, 2023). "While low plasma ADA2 levels and elevated TNFα are diagnostic markers for DADA2, immunological screening is essential to avoid delays, especially when pancytopenia is the sole clinical presentation in disorders that impact both marrow cell development and immune function." (PMID 40975757, 2025).
rheumatoid arthritis (3 papers, 2020 to 2022). A chronic, systemic autoimmune disorder characterized by inflammation in the synovial membranes and articular surfaces. "The inflammatory cytokine TNF-α has a role in both innate and adaptive immunity, underlying the efficacy of TNF inhibitors in patients with autoimmune conditions like rheumatoid arthritis (RA) and autoinflammatory conditions like Deficiency of ADA2 (DADA2)." (PMID 35281022, 2022). "ADA2 activity has also been studied in a number of adult rheumatic conditions and increased adenosine deaminase activity is observed in individuals with rheumatoid arthritis (RA), systemic lupus erythematous (SLE), and Crohn’s disease." (PMID 32650798, 2020).
Wiskott-Aldrich syndrome (3 papers, 2020 to 2025). Wiskott-Aldrich syndrome (WAS) is a primary immunodeficiency disease characterized by microthrombocytopenia, eczema, infections and an increased risk for autoimmune manifestations and malignancies. "The differential diagnosis should include ADA2 deficiency, CVID (38%) Wiskott-Aldrich syndrome (WAS) (26%)." (PMID 33193364, 2020).
anemia (2 papers, 2021). A reduction in the number of red blood cells, the amount of hemoglobin, and/or the volume of packed red blood cells. "Overall, our observations may have translational relevance as several of the recently described patients with ADA2 deficiency (DADA2) were diagnosed during the first two months of life after presenting with fever and/or anemia." (PMID 34122398, 2021).
autoinflammatory syndrome (2 papers, 2019 to 2022). A group of disorders of the innate immune system characterized by attacks of seemingly unprovoked inflammation without significant levels of either autoantibodies or autoreactive T cells more characteristic of autoimmune disease. "Adenosine deaminase 2 (ADA2) deficiency is an inherited autoinflammatory syndrome caused by a defect in the ADA2 gene." (PMID 36528591, 2022).
Cutaneous abscess (2 papers, 2021 to 2022). A circumscribed area of pus or necrotic debris in the skin (within the epidermis or dermis). "Skin involvement was remarkable in TNFAIP3 and ADA2 deficiencies, but it was one of the most common manifestations among ALPS-like disorders, mainly in form of non-infectious skin rashes, psoriatic-like lesions, skin abscess, severe eczema and skin warts (usually due to papilloma virus infection)." (PMID 34447369, 2021).